TNF (tumor necrosis factor)
Diseases named in the same sentence as TNF in open-access papers (continued):
Sharing a sentence is not in itself a finding about the gene and the disease.
COVID-19 (continued). "Based on the 39 core common genes, immune system, cytokine/inflammatory response, signaling by interleukins, TNF-α signaling via NF-kB, IL-6/JAK/STAT3 signaling, TLR signaling, and AGE-RAGE signaling pathways, etc., are found as links between CVD and COVID-19." (PMID 34067609, 2021). "In support of histological evidence of lung epithelium damage, concentrations of cell death–related proteins tumor necrosis factor–α (TNFα), caspase 8, TRAIL, EDAR, and NCR1 were altered in plasma from patients with COVID-19 relative to normal controls." (PMID 34648357, 2021). "Whereas the airway DEG profile indicated regulation by both inflammatory and inhibitory cytokines, the COVID-19 lung UPRs were markedly inflammatory, including, NFκB, IL12, TNF, IL1B, and multiple Type I IFNs." (PMID 33782412, 2021). "This analysis shows that plasma levels of HA and hyaluronidase in patients with COVID-19 each are correlated with inflammatory cytokines known to have roles in either HA synthesis or degradation such as IL-6, IL-8, MCP-1, TNF-α, and IP10." (PMID 34314391, 2021). "Various inhibitory antibodies directed to these targets have already been evaluated in COVID-19 patients, such as anti-IL1® (canakinumab), anti-IL6R (tocilizumab, sarilumab) or anti-TNFα (infliximab, adalimumab) antibodies." (PMID 34293006, 2021). "Correspondingly, there are increased serum levels of TNF, IFNG, and IL6 in confirmed COVID-19 patients." (PMID 33737867, 2021). "Potential mechanistic pathways of HJSS in COVID-19-related ARDS were primarily related to the HIF-1, NOD-like receptor, TNF, T cell receptor, sphingolipid, PI3K-Akt, toll-like receptor, VEGF, FoxO, and MAPK signaling pathways." (PMID 34220524, 2021). "IL-6, CXCL10, CXCL9, CCL2, IL1-Ra, IL-10, G-CSF and TNF-α were the cytokines with the highest contribution to dimension 2 in the PCA and were significantly increased in acute COVID-19 patients in comparison to HC." (PMID 34572439, 2021). "It is important to note that levels of interleukins, TNFα, and CRP were tested almost exclusively in hospitalized COVID-19 patients." (PMID 34228746, 2021). "These pathways include processes crucial for COVID-19 severity including T cell mediated immunity, macrophage activation and cytokine production (IL1, IL6, IL8 and TNF, among others)." (PMID 34075090, 2021). "Our data demonstrated that after being induced by Prot_S, Calu-3 cells showed the upregulation of TNFα, IL6, IL1β, and IFNγ, which is in line with the clinical situation of patients with COVID-19." (PMID 34074129, 2021). "In our cohort of moderately and severely sick hospitalized COVID-19 patients, IL-6, MIG, TNF-α, IL-8, IL-18 and IP-10 were highest in patients with severe COVID-19." (PMID 34539644, 2021). "This predictive model assembling severe COVID-19-related proteins supports a role for known contributors to the cytokine storm such as IL1β, IL6, TNFα, JAK2, but also less prominent actors such as IL17, IL23 and C5a." (PMID 34293006, 2021). "The increase in blood concentrations of different cytokines such as interleukins and chemokines such as IL-6, IL-8, IL-10, TNF-α, IL-1β, IL-2, IP-10, MCP-1, CCL3, CCL4, and CCL5 has been described for COVID-19 patients." (PMID 34262570, 2021). "Individuals with severe COVID-19 have markedly reduced numbers of CD4+ and CD8+ T cells, and lymphocyte counts negatively correlate with levels of serum IL-6, IL-10, and TNF-α." (PMID 34440767, 2021). "Another study revealed that peripheral blood immune cells from severe COVID-19 patients have diminished type-I IFN response but enhanced pro-inflammatory IL-6 and TNF-α responses." (PMID 34835108, 2021). "Increased cytokine secretion, including IL-2, IL-4, IL-6, IL-10, tumor necrosis factor (TNF)-α, and IFN-γ, in COVID-19 patients has been reported." (PMID 33445583, 2021).
COVID-19 (continued). "KEGG analysis suggested that HJSS improved COVID-19-related ARDS by regulating hypoxia-inducible factor (HIF)-1, NOD-like receptor, TNF, T cell receptor, sphingolipid, PI3K-Akt, toll-like receptor, VEGF, FoxO, and MAPK signaling pathways." (PMID 34220524, 2021). "Elevated levels of pro-inflammatory cytokines including tumor necrosis factor alpha (TNF-α), interleukin (IL)-1 and IL-6, as well as lymphopenia, are the most prevalent cytokine profile shifts in COVID-19 patients with severe or terminal disease." (PMID 34205044, 2021). "Individuals in cohort one with acute COVID-19 had coagulopathy (with increased D-Dimer and fibrinogen), a marked pro-inflammatory response (elevated CRP, IL-6, TNF-α, IL-8 and IL-1β) and lymphopenia, with an increase in the neutrophil: lymphocyte ratio." (PMID 34025675, 2021). "The UC-MSC treatment group is characterized by a reduction in the levels of inflammatory molecules, including IFN-γ, IL-6, and TNF-α cytokines, and regulated on activation, normal T cell expressed and secreted chemokine (RANTES) in COVID-19 patients." (PMID 34315546, 2021). "Many cytokines in COVID-19 patients were significantly different from those in healthy individuals, including IL-2, IL-4, IL-6, CCL2, IFN-γ, and TNF-α." (PMID 34489974, 2021). "In severe COVID-19 cases, hyperactivation of T-cells, especially CD8+ T-Cells, leads to the release of a higher level of interferon (IFN)-γ, interleukin (IL)-2, and tumor necrosis factor (TNF)-α." (PMID 34960133, 2021). "Studies have shown a strong correlation between the severity of COVID-19 and concentrations of different cytokines, such as IL2, IL7, IL10, GCSF, MCP1, and TNF-alpha." (PMID 33796097, 2021). "In patients with cytokine storm secondary to COVID-19, elevated serum cytokine levels are mainly related to IL-1β, IL-6, CXCL10, TNF-α, IFN-γ, macrophage inflammatory protein (MIP) 1α and 1β, and VEGF." (PMID 33669011, 2021). "It remains to be defined why COVID-19 patients had severe and critical clinical characteristics independent of circulating levels of inflammatory cytokines (IFN-γ, TNF-α, IL-2, IL-4 and IL-10)." (PMID 34123873, 2021). "Our findings of raised TNF-α and IL-6 levels after SARS-CoV-2 infection are comparable to other research and are consistent with the cytokine storm described in COVID-19." (PMID 34884175, 2021). "In comparison to patients with COVID-19 in general wards, intensive care unit (ICU) patients showed high titers of serum MCP-1, IP-10, TNF-α, macrophage inflammatory protein-1A, and granulocyte colony-activating factor." (PMID 33946736, 2021). "The data discussed here extend these observations, showing that the CD3+CD4+ and CD16+CD56+ lymphocyte counts were higher but the TNF-α and IFN-γ were lower in COVID-19 patients compared with those of CAP patients." (PMID 34150910, 2021). "COVID-19 patients display high levels of both inflammatory cytokines and chemokines (IL-1a/β, IP-10, MCP-1), with severe cases showing elevation in TNFα, IL-1, IL-6, IL-18, IL-8, IL-10, MCP-1 and MIP-1A." (PMID 33803997, 2021). "In the event of severe lung infection due to COVID-19, hyper-production of inflammatory markers such as IFN-γ, TNFα, IL-1, IL-6, and IL-12 are evident." (PMID 34066983, 2021). "The therapeutic efficacy of SHXP against COVID-19 is likely mediated via the regulation of 4 targets, namely, IL6, IL10, VEGFA, and TNF." (PMID 34941025, 2021). "Cytokines IL-1, IL-6, TNF, signal transducer and transcriptional activator 3 (STAT3), NF-κB, and lipopolysaccharides were the highest regulators of thrombotic markers in COVID-19 patients with severe-to-critical disease." (PMID 33995341, 2021). "We found the majority of common targets between GA and COVID-19 to be upregulated in the IL-1, VEGF, JAK-STAT, TNFα, and TLR pathway families." (PMID 34177566, 2021).
COVID-19 (continued). "The main lymphocyte subpopulations (CD3+CD4+, CD16+CD56+, and CD4+/CD8+ ratio) and cytokines (TNF-α and IFN-γ) of COVID-19 patients were significantly different from that of CAP patients." (PMID 34150910, 2021). "Longitudinal studies have demonstrated gradual declines of serum concentration of inflammatory biomarkers including IL-6, IL-8, tumor necrosis factor-α, and high-sensitivity C-reactive protein (hs-CRP) at the late stage of illness in COVID-19 survivors." (PMID 34912863, 2021). "Our further analysis confirmed a positive correlation of the plasma Gal-9 concentration with IL-6, TNF-α, IP-10, MIP-1α, and MCP-1 in COVID-19 patients." (PMID 33947753, 2021). "Involved cytokines seem to be different, with a more oriented IL-6, TNF, interferon and CXCL5 profile in COVID-19 and a more defined role for IL-6 and IL-10 in influenza." (PMID 34524562, 2021). "MHD patients with COVID-19 had elevated infection-related biomarkers, including CRP, ESR, procalcitonin, IL-6, IL-2R and TNF-α, which likely reflected an exacerbated inflammatory response." (PMID 33967613, 2021). "The efficiency of the COVID-19 vaccine may be expected to be lower in patients treated with IL-1 blockade, but limited evidence shows that patients with chronic rheumatic diseases under immunosuppression with either anti-TNF agents or IL-17 blockade develop adequate levels of antibody responses." (PMID 35154066, 2021). "Although IL-1β, IL-6, and TNFα are well-established to influence nociceptive hypersensitivity, the possibility that additional or alternative mediators may also be driving nociceptive sensitivity in patients with COVID-19 cannot be discounted, especially in severe and critical infection." (PMID 33458558, 2021). "TNF-a and IFN-γ mediated inflammatory cell death signaling pathways to limiting tissue damage in COVID-19 patients." (PMID 34489974, 2021). "Elevated serum levels of IL-6 and other pro-inflammatory cytokines, such as TNF-α and IFN-γ, are hallmarks of systemic inflammation of COVID-19, contributing to disease severity and adverse clinical outcomes." (PMID 34834033, 2021). "Cytokines such as TNF- α, CCL2, CXCL8, and IL6, which show high levels in COVID-19 patients requiring ICU admission, can predictably be inhibited by the bioactive components." (PMID 34513735, 2021). "It is reported that a marked increase in inflammatory factors occurs in COVID-19, including C-reactive protein (CRP), IL-6, TNF-α, etc.." (PMID 34335279, 2021). "Spike protein from SARS-CoV-2 showed to be a good T-cell stimulation for COVID-19, with high production of IFN-γ, IL-2, and TNF by CD4+ T cells, characterizing the predominant response of Th1 cells." (PMID 34571855, 2021). "Increasing evidence has shown that a number of cytokines, including interleukins (IL-1, IL-6, IL-8), tumor necrosis factor (TNF), a-nd interferon (IFN) displayed significant changes in COVID-19 patients." (PMID 34109148, 2021). "COVID-19-related CRS patients exhibited increased plasma levels of IL-2, IL-7, IL-10, G-SCF, MCP-1, MIP-1α, and TNF-α." (PMID 34884813, 2021). "Immune system impairment is associated with T2DM and abnormal secretion of pro-inflammatory cytokines, particularly TNFα and IFN in COVID-19 patients." (PMID 34205044, 2021). "Almost all seropositive and 17.9% of seronegative patients on BCDT, enriched for a history of COVID-19-like symptoms, developed anti-SARS-CoV-2 T cell memory, and T cells displayed functional similarity to controls producing IFN-γ and TNF." (PMID 34490414, 2021). "High expression of TNF-α and IFN-γ will aggravate SARS-CoV-2-induced inflammatory cell death in old RMs, and will eventually promote COVID-19 progress." (PMID 34471088, 2021). "The hyperproduction of proinflammatory cytokines, such as IL-1, IL-6, IL-12, interferon γ (IFN-γ) and tumor necrosis factor α (TNF-α), which preferentially target the pulmonary tissue, seems to significantly worsen the prognosis of COVID-19 patients." (PMID 33916917, 2021).
COVID-19 (continued). "In COVID-19, the expression of the inhibitory marker KLRC1 (also known as NKG2A) leads to decreased NK cells cytotoxic activity by affecting the IFNγ and TNFα pathways." (PMID 34603282, 2021). "In our model, VPA reduces the expression of the pro-inflammatory cytokines TNF-α and IL-6 even after SARS-CoV-2 infection, making VPA a promising candidate for the treatment of COVID-19 patients." (PMID 34635175, 2021). "The pooled analysis showed decreased effects on TNF-α between the CHM and control treatment groups among COVID-19 patients, of which, the combined WMD of TNF-α was −3.80 (95% CI, −5.96, −1.65, P = 0.0005; random effect model)." (PMID 35127733, 2021). "We observed activation of NF-κB signaling and activation of target genes, TNF-α, IL-6, and CCL5, following exposure of hepatocytes to exosomes isolated from plasma of COVID-19 patients." (PMID 33804769, 2021). "Our present results identified obvious elevations of various cytokines in patients with severe COVID-19, including IL-1α, IL-1β, IFN-γ, TNF-α, IL-2, IL-4, IL-6, IL-10, and IL-17A." (PMID 34113636, 2021). "An upregulation of proinflammatory cytokines including TNF, IL-6, and IL-10 indicates the activation of a specific immune pathway probably leading to a decrease of AQP1 in patients suffering from COVID-19." (PMID 33918079, 2021). "This process is modulated by proinflammatory mediators, such as TNFα, CCL3, and CCL2 (MCP-1), leading to hypoxia, ARDS, and possibly death for COVID-19 patients." (PMID 34616396, 2021). "During COVID-19 in patients in a severe/critical state of health, levels of pro-inflammatory cytokines IL-6, IL-10, IFN, and TNF-α are elevated." (PMID 34578858, 2021). "Several pro-inflammatory cytokines, including interleukin-6 (IL6), tumor necrosis factor-alpha (TNF-α), and transforming growth factor-beta (TGF-β), contribute to the inflammatory injury of lungs in COVID-19 patients during the CRS." (PMID 33815126, 2021). "Clinical studies have indicated that the levels of IFN-γ, IL-6, TNF-α, IL-2, MCP-1, and other pro-inflammatory cytokines are significantly increased in severe or critical COVID-19 patients." (PMID 33995078, 2021). "The proinflammatory cytokines TNF-α, IL-1β, IL-8, IL-6, and IL12-B (P < 0.05) were increased in patients who had contracted COVID-19." (PMID 33819170, 2021). "We identified TNF and INSR as key targets for diabetic COVID-19 patients based on our comorbid condition-specific target identification." (PMID 34067609, 2021). "In this study, we investigated the effect of pre-analytical sample handling variations on levels of COVID-19-relevant cytokines IFN-γ, IL-10, IL-12p70, IL-17A, IL-6 and TNF-α." (PMID 34289718, 2021). "In serum of patients with severe COVID-19, the levels of IL-6, MIG, TNF-α, IL-8, IL-18 and IP-10 were higher than in the healthy controls (–G), while in moderate disease only the levels of IL-18, IL-8 and IP-10 were higher." (PMID 34539644, 2021). "In the clinical treatment of patients with COVID-19, Xuebijing Injection mainly inhibited IL6, TNF-α, MCP1, mip2, and IL10 to inhibit inflammatory response." (PMID 34335247, 2021). "In particular, TNF pathway has been reported to be involved in a variety of physiological and pathological processes, such as cell proliferation, apoptosis, and modulation of immune responses and induction of inflammation, so it may play an important role in the treatment of COVID-19." (PMID 33658066, 2021). "Many cytokines have been reported at elevated levels in COVID-19 cases, including IL1-β, IL-6, IL-7, IL-8, and tumor necrosis factor-α (TNF-α)." (PMID 34205928, 2021). "It should be noted that the cytokine profile similar to MAS/sHLH has also been observed in COVID-19 patients, especially the increase of IL1β, IL2, IL6, IL17, IL8, TNF and CCL2." (PMID 34912345, 2021). "In COVID-19, the CD4 response was characterized by limited expression of IFN-γ and was enriched in cells coexpressing IL-2 and TNF-α." (PMID 33945513, 2021).
COVID-19 (continued). "IL6, CXCL8, EGFR, FOS, PIK3R1, and NFKB1 were identified as common targets from the common pathways between cancers and COVID-19 (signaling by interleukins, TLR signaling, TNF-α signaling via NF-kB)." (PMID 34067609, 2021). "Regarding the general cell response, we present the following findings: autopsies of patients with COVID-19 revealed increased cell exhaustion and SARS-CoV-2 CD4+ expressing IFN-γ, TNF-alpha, and IL-2 indicating a Th1 cellular response." (PMID 34571855, 2021). "The dysregulated release of cytokines, including tumor necrosis factor (TNF)-α, interferon (IFN)-γ, interleukin (IL)-1β, and IL-6, are related to a poor prognosis in patients with COVID-19." (PMID 34834939, 2021). "It was recently reported that in patients with severe COVID-19 the levels of IL-2, IL-7, IL-10, GSCF, IP10, MCP-1, MIP1A, and TNF-α are dramatically elevated." (PMID 34361736, 2021). "It is estimated that 10–15% of patients with severe COVID-19 progressed to ARDS triggered by cytokine storm, due to overproduction of IL-6, IL-8, IL-10, IL-17, and TNF-α." (PMID 34445556, 2021). "Therefore, anti-TNF therapies may reduce many pathogenic proinflammatory cytokines during SARS-CoV-2 infection and be an effective immunomodulatory approach for treatment of COVID-19 patients." (PMID 34975885, 2021). "Increased IL-2, IL-6, TNF-α, and IFN-γ were detected in trophoblast cells and maternal blood of COVID-19 placentas." (PMID 35071136, 2021). "Upon stimulation with IL-12/IL-18, the percentage of Granzyme B (p = 0.007), IFN-γ (p = 0.008), TNF-α (p < 0.001) and Perforin (p = 0.03) expressing MAIT cells was significantly lower in COVID-19 patients compared to control uninfected individuals." (PMID 34238985, 2021). "Thus, anti-TNFα antibodies, and adalimumab in particular thanks to its excellent safety profile, could inhibit the basic mechanisms of COVID-19, and could be potentially useful in managing/preventing COVID-19-driven pneumonia." (PMID 33544720, 2021). "In fact, patients with COVID-19 display a pro-inflammatory (IL-1β, IL-6, IL-7, IL-8, IL-9, FGF, G-CSF, GM-CSF, IFN-ɣ, CXCL10, CCL2, CCL3, CCL4, PDGF, TNFα, and VEGF) and regulatory cytokine profile (IL-10 and TGFβ; cytokine storm)." (PMID 33995342, 2021). "Among them, IL6, tumor necrosis factor alpha (TNFα), MAPK1, MAPK14, MAPK8, PTGS2, IL2 and PPARG were the predominant targets for Xuebijing to treat COVID-19." (PMID 34539389, 2021). "Infrared light therapy has been shown to decrease TLR4-dependent induction of IL-6, IL-8, TNF-α, INF-α, and INF-β in COVID-19 hyperinflammation." (PMID 34835108, 2021). "In COVID-19, the upregulated activity of ADAM17 increases ACE2 shedding, which in turn leads to higher sACE2 levels, and to the increase of TNF-α production." (PMID 34685735, 2021). "Recently, the neutralization of both TNF-α and IFN-γ has been found to benefit patients with COVID-19 or other cytokine storm-drive syndromes by limiting inflammation and tissue damage." (PMID 34260666, 2021). "Previous studies reported an increase in tumor necrosis factor (TNF)-α and interferon (IFN)-γ production by CD4+ T cells after AstraZeneca-Oxford COVID-19 vaccine." (PMID 35004790, 2021). "A main factor contributing to COVID-19 severity is believed to be development of the cytokine storm, the uncontrolled release of various inflammatory markers (such as CRP, IL-6, ferritin, tumor necrosis factor α or neutrophil-to-lymphocyte ratio (NLR))." (PMID 34578898, 2021). "We detected minimal TNF-mediated or IL-6-mediated JAK–STAT signaling activation in circulating monocytes and DCs, but this was upregulated by COVID-19 BAL MPs." (PMID 33879890, 2021). "TNF and IL6 were previously shown to be among the master cytokines involved in COVID-19 related hyperinflammation." (PMID 34088975, 2021).